SLC3A2 (solute carrier family 3 member 2)
Diseases named in the same sentence as SLC3A2 in open-access papers (continued):
Sharing a sentence is not in itself a finding about the gene and the disease.
ovarian carcinoma (11 papers, 2012 to 2026). A malignant neoplasm originating from the surface ovarian epithelium. "Mechanistic studies showed that the axis of METTL5‐ATF4‐SLC7A11/SLC3A2 modulates tumor sensitivity to T cell‐mediated antitumor immune activity in ovarian cancers." (PMID 41042068, 2025). "It has also been reported that inhibition of SLC3A2 expression significantly reduces the survival rate of ovarian cancer cells treated with cisplatin and promotes cell migration." (PMID 35567291, 2022). "SLC3A2, which was identified by us as a protective factor for ovarian cancer prognosis, was also reported as a protective factor for ovarian cancer cisplatin sensitivity." (PMID 32647070, 2020). "Overall, our data indicate that the axis of METTL5‐ATF4‐SLC7A11/SLC3A2 plays a vital role in promoting immune resistance in ovarian cancer models and patients, and targeting METTL5 could improve the effectiveness of immunotherapy in OC patients." (PMID 41042068, 2025). "In addition, through the literature review, we found that except CYBB, VDAC2, IDH1, MT1G, SLC1A4, PCK2, SLC3A2, the prognostic value of other FRGs in ovarian cancer has been reported, which provided a possibility for constructing a prognostic model." (PMID 36386203, 2022). "For example, ZEB1 promotes chemoresistance to cisplatin by suppressing SLC3A2 in ovarian cancer." (PMID 36512117, 2022). "The OS of ovarian cancer patients prolonged with the high-expression of ATG7, G6PD, SLC3A2, MAP1LC3C and PTGS2, but shrank with the increased expression of NFS1, VDAC2, ACSL3." (PMID 35039008, 2022).
colon carcinoma (10 papers, 2019 to 2025). "The results showed that the most disulfidptosis associated genes was upregulated except SLC7A11 and SLC3A2, which confirmed the involvement of disulfidptosis in colon cancer." (PMID 38802854, 2024). "This suggests that SLC3A2 can serve as a receptor for targeted drug delivery in colon cancer cells and that its downregulation, in combination with anticancer drug treatment, increases the therapeutic efficacy of the anticancer drug." (PMID 36770817, 2023). "While SLC3A2 is only weakly expressed on the basolateral membranes in healthy colon epithelial cells, it is distinctly overexpressed on both apical and basolateral membranes in colon cancer, where it plays a special role in the development of colon cancer." (PMID 36770817, 2023). "SLC1A4, SLC2A1, SLC3A2, SLC6A8, and SLC7A5 are transported as mRNAs by lung- and colon cancer-related exosomes." (PMID 41440381, 2025).
prostate carcinoma (10 papers, 2012 to 2026). A carcinoma that arises from epithelial cells of the prostate gland. "Several of the identified cell surface markers have known associations with prostate cancer and metastasis including CD59, 4F2 cell-surface antigen heavy chain (SLC3A2) and adhesion G protein-coupled receptor E5 (CD97)." (PMID 38053024, 2023). "4F2 cell-surface antigen heavy chain (SLC3A2), a single-pass type II membrane protein which is known to promote prostate cancer progression, was detected with 14 biotinylation sites." (PMID 38053024, 2023). "Despite the proven tumorigenic role of SLC3A2 in a number of cancers including head and neck squamous cell carcinomas (HNSCC), it is also a novel therapeutic approach for advanced prostate cancer." (PMID 35818395, 2022). "Slc3a2 has been found to be upregulated in human prostate cancer cells in an ATF4‐mediated way 26 and we also found induced gene expression of Slc3a2 in the hypothalamic cell line." (PMID 28174690, 2017). "To further test the GCN2/SLC3A2 (4F2) model, we derived a gene signature from GCN2-dependent transcripts from our RNA-seq analysis and measured a significant correlation with SLC3A2 (4F2) expression (r = 0.53, p < 0.0001) using a cohort of prostate cancer patients (PRAD) from the TCGA database." (PMID 36107759, 2022).
bladder cancer (9 papers, 2013 to 2024). "Therefore, our results indicate that SLC3A2/SLC7A5 exert the enormous function on promoting the malignant progression of bladder cancer cells in vitro and vivo." (PMID 38267663, 2024). "Our data suggests that targeting METTL3/ALKBH5 and their downstream genes SLC3A2/SLC7A5 may be a potential therapeutic strategy for bladder cancer." (PMID 38267663, 2024). "Taken together, our results revealed that the m6A modification-mediated SLC3A2/SLC7A5 translation promoted 3-MC-induced uroepithelial transformation, suggesting that targeting m6A modification of SLC3A2/SLC7A5 may be a potential therapeutic strategy for bladder cancer related to PAHs." (PMID 38267663, 2024). "Altogether, our data identify METTL3/ALKBH5 and SLC3A2/SLC7A5 as the potential therapeutic targets and pave the way for future development of therapy for bladder cancer related to PAHs." (PMID 38267663, 2024). "During the malignant transformation, dysregulation of METTL3/ALKBH5 induced the up-regulation of m6A levels on SLC3A2/SLC7A5 mRNA in cells, which promoted translation and expression of SLC3A2/SLC7A5, and thus accelerated bladder cancer growth and metastasis." (PMID 38267663, 2024). "Our study has identified four disulfidptosis suppressor genes, namely SLC7A11, SLC3A2, RPN1, and NCKAP1, which play significant roles in the development and immune infiltration of bladder cancer." (PMID 37152941, 2023).
head and neck squamous cell carcinoma (9 papers, 2012 to 2025). A squamous cell carcinoma that arises from any of the following anatomic sites: lip and oral cavity, nasal cavity, paranasal sinuses, pharynx, larynx, and salivary glands. "Accordingly, SLC3A2 has been found to regulate radiosensitivity in head and neck squamous cell carcinoma." (PMID 38281999, 2024). "SLC3A2 has also been used as a cancer stem cell marker in head and neck squamous cell carcinoma." (PMID 38069306, 2023). "In this study, we identified the high expression of SLC3A2 in NPC and head and neck squamous cell carcinoma (HNSC) and analyzed its potential mechanism and correlation with patient prognosis." (PMID 39926285, 2025). "Some studies have found that SLC3A2 has a carcinogenic effect in many kinds of cancers, including oropharyngeal cancer, head and neck squamous cell carcinomas (HNSCC), and renal cancer cell, which contributes to inferior prognosis of cancer patients, and may act as a predictive marker." (PMID 33996564, 2021).
breast tumor (8 papers, 2015 to 2025). "SLC7A5, SLC1A5, GLS and PIK3CA were significantly expressed in breast tumours with high expression of SLC3A2 (p < 0.001), while the low expression was associated with high levels of p-mTORC1 (p < 0.001)." (PMID 29545595, 2018). "Our study revealed that SLC7A11 and SLC3A2 were found to be upregulated in endocrine resistant breast tumors and cancer cells." (PMID 39833180, 2025). "Compared with normal breast tissue, the expression of xCT components SLC7A11 and SLC3A2 is increased in a subset of patient breast tumor tissues, and their co-expression is closely related to the expression of GPX4." (PMID 35057861, 2022). "We observe that expression of the xCT components SLC7A11 and SLC3A2 are elevated in a subset of patient breast tumor tissues compared to normal breast tissue, and that their coordinated expression tightly correlates with GPX4 expression." (PMID 33672555, 2021). "Furthermore, upregulation of SLC7A11 and SLC3A2 proteins was observed in endocrine-resistant breast tumors compared with primary ER+ breast tumors." (PMID 39833180, 2025). "Apart from SLC7A8, all the following amino acid transporters, SLC7A5, SLC3A2, SLC7A11 and SLC38A2, were significantly expressed in breast tumours with high SLC1A5 expression (P < 0.01)." (PMID 39843491, 2025). "When directly examining protein levels from patient-derived breast tumor samples and normal breast tissues, we found that the expression levels of the xCT subunits, SLC7A11 and SLC3A2, were significantly upregulated in breast tumor tissues compared with normal tissues." (PMID 33672555, 2021).
colitis (8 papers, 2012 to 2025). Inflammation of the colon. "Overexpression of SLC3A2 in gastrointestinal epithelium induced tumorigenesis by production of pro-inflammatory mediators and stimulating cell proliferation, whereas down-regulation of SLC3A2 attenuated inflammatory responses and resistance to colitis-associated tumorigenesis." (PMID 29179459, 2017). "It has been reported that SLC3A2 regulates the expression of cyclin D1 in IECs to participate in mouse colitis." (PMID 39688910, 2024). "Collectively, our in vitro and in vivo data suggest that NEDD4L modulated SLC3A2 ubiquitinoylation to regulate DSS-induced colitis." (PMID 39688910, 2024). "Our study revealed a positive correlation between NEDD4L protein expression and SLC3A2 in humans with IBDs and CRC, demonstrating that the NEDD4L/SLC3A2/GPX4 axis played an important role in colitis and CAC." (PMID 39688910, 2024). "SLC3A2 is a potential substrate of NEDD4L in DSS-induced colitis." (PMID 39688910, 2024). "However, our unbiased ubiquitination MS sequencing data and in vivo experiments support that SLC3A2/GPX4–mediated lipid peroxidation production signaling played a dominant role in controlling colitis and CAC." (PMID 39688910, 2024). "A similar antibody-mediated targeting strategy was used with PLGA nanoparticles to deliver SLC3A2 siRNA into intestinal cells of mice with colitis, thereby targeting SLC3A2 on the surface of colon epithelial cells and macrophages, where it is overexpressed due to inflammatory processes." (PMID 36770817, 2023). "Similarly, DSS-induced colitis suppressed the expression of key ferroptosis-regulating proteins such as GPX4, SLC7A11, and SLC3A2, while elevating HO-1 levels as a compensatory response to oxidative stress." (PMID 39940407, 2025). "Based on the combined analysis of quantitative ubiquitination MS and interaction MS, we hypothesized that NEDD4L might interact with SLC3A2 and regulate its ubiquitination, triggering IEC ferroptosis and aggravating DSS-induced colitis." (PMID 39688910, 2024). "Additionally, Nedd4l KO in mice significantly enhanced DSS/TNBS–induced colitis and AOM/DSS–induced CAC by triggering SLC3A2-mediated ferroptosis." (PMID 39688910, 2024).
multiple myeloma (8 papers, 2014 to 2026). "SLC3A2, which acts as an amino acid exchanger, is one of the most abundant proteins on the surface of myeloma cells, providing support for the secretion of copious amounts of antibodies by MM cells." (PMID 40308607, 2025).
liver cancer (7 papers, 2022 to 2025). An epithelial or non-epithelial malignant neoplasm that arises from the liver. "In liver cancer, SLC3A2 promotes the ceramide/sphingosine/sphingosine 1-phosphate axis in increasing liver cancer progression." (PMID 38705513, 2024). "Liver-cancer-cell-derived exosomal miR-142-3p induces ferroptosis in M1-type macrophages by downregulating SLC3A2." (PMID 38892270, 2024). "Dihydroartemisinin promotes the antiproliferation and ferroptosis of liver cancer cells by upregulating the ferroptosis-inducing ATF4 gene and downregulating ferroptosis-inhibiting genes (GPX4, SLC7A11, and SLC3A2)." (PMID 38892270, 2024). "The data revealed that the expression level of HAAO in liver cancer is negatively correlated with ferroptosis‐resistant genes including SLC7A11, SLC3A2, and ACSL3, whereas positively correlated with ferroptosis‐sensitive gene ACSL1." (PMID 36627132, 2023).
neuroblastoma (7 papers, 2011 to 2025). Neuroblastoma (NB) is the most common solid, extracranial childhood tumor. "Survival analyses in the SEQC cohort confirmed our prior findings that elevated expression of SLC3A2 is associated with worse event‐free and overall survival in neuroblastoma." (PMID 39981745, 2025). "Similarly to DIPG we also found higher SLC3A2 expression in HGGs comparing to other brain tumors and high-risk neuroblastoma." (PMID 33579942, 2021). "We silenced SLC3A2 expression in non‐MYCN‐amplified (SH‐SY5Y) as well as MYCN‐amplified (KELLY) neuroblastoma cells and subsequently measured putrescine and spermidine uptake." (PMID 39981745, 2025). "We previously identified SLC3A2 as a candidate polyamine transporter in neuroblastoma cells and established members of the P5B‐ATPase family, as key components of the mammalian polyamine transport system." (PMID 39981745, 2025). "To examine which polyamine transporters play a role in basal and DFMO‐induced polyamine uptake, we started by confirming our earlier discovery that SLC3A2 contributes to polyamine uptake in MYCN‐amplified neuroblastoma cells." (PMID 39981745, 2025). "In this study we explored two candidate polyamine transporters, SLC3A2 and ATP13A3, as their higher expression is associated with an inferior outcome in neuroblastoma patients." (PMID 39981745, 2025). "siRNA‐mediated silencing significantly decreased SLC3A2 mRNA expression in both neuroblastoma cell lines 48–72 h after transfection, which attenuated putrescine and spermidine uptake levels." (PMID 39981745, 2025). "Nevertheless, in a direct side‐by‐side comparison, ATP13A3 has a stronger impact on polyamine uptake than SLC3A2 in neuroblastoma cells under basal and DFMO‐treatment conditions." (PMID 39981745, 2025). "Recently, CD98 (4F2 heavy chain antigen, encoded by SLC3A2) has been identified as a key polyamine transporter in neuroblastoma." (PMID 32824193, 2020). "We previously uncovered a putative role for SLC3A2 in polyamine transport in neuroblastoma." (PMID 39981745, 2025). "Evaluating SLC3A2 expression from the ZCC precision medicine platform, we also found significantly higher expression in the cohort of DMGs compared to other high-risk pediatric cancers including relapsed/refractory high-risk neuroblastoma." (PMID 33579942, 2021). "SLC3A2 is significantly overexpressed in DIPG and HGG compared with high-risk neuroblastoma, which may explain the enhanced in vivo efficacy seen in DIPG." (PMID 33579942, 2021). "We have previously reported that exposure of SH-SY5Y neuroblastoma cells to unconjugated bilirubin (UCB) resulted in a marked up-regulation of the mRNA encoding for the Na+ -independent cystine∶glutamate exchanger System Xc− (SLC7A11 and SLC3A2 genes)." (PMID 22216172, 2011). "Similarly, while the silencing of either ATP13A3 or SLC3A2 in neuroblastoma cells resulted in reduced polyamine uptake, only the silencing of ATP13A3, and not of SLC3A2, was sufficient to prevent the compensatory increase in polyamine uptake under DFMO treatment." (PMID 39981745, 2025). "We identified SLC3A2 as a potential Anaplastic Lymphoma Kinase (ALK) interacting partner in a BioID-proximity labeling screen in neuroblastoma (NB) cells." (PMID 38858548, 2024). "SLC3A2, ATP13A2, ATP13A3 are abundantly expressed in neuroblastoma tumors, while ATP13A4 and ATP13A5 expression is low." (PMID 39981745, 2025). "Our analysis suggests that ATP13A3 is a MYC target gene like ODC1 and SLC3A2 and that high expression of ATP13A3 represents an independent prognostic predictor of poor outcome in neuroblastoma." (PMID 39981745, 2025). "The MYCN‐polyamine axis is of particular significance in neuroblastoma research, since multiple genes within the polyamine pathway, including ODC1 and SLC3A2, are direct targets of MYCN." (PMID 39981745, 2025).
neuroblastoma (continued). "Our database analyses revealed that ATP13A2 is expressed to similar levels as ATP13A3 in neuroblastoma patients and, contrary to ATP13A3 and SLC3A2 expression, high expression of ATP13A2 is predictive of a better outcome in patients." (PMID 39981745, 2025). "Interestingly, we observed that, as previously found for SLC3A2, ATP13A3 expression was significantly higher in MYCN‐amplified versus non‐MYCN amplified neuroblastoma tumors." (PMID 39981745, 2025). "In investigating and comparing the potential roles of SLC3A2 and ATP13A3 in polyamine uptake under basal and DFMO‐treated conditions, our work highlights notable similarities and differences in the role of both candidate transporters in neuroblastoma." (PMID 39981745, 2025). "In this study, we discovered that high ATP13A3 expression is associated with worse overall and event‐free survival in neuroblastoma patients and that ATP13A3, but not SLC3A2, is a primary mediator of DFMO‐induced polyamine uptake in this disease." (PMID 39981745, 2025). "In light of the finding that neuroblastoma cells treated with DFMO compensate for a decrease in intracellular polyamines by augmenting polyamine uptake, we next assessed whether SLC3A2‐mediated polyamine uptake contributes to the DFMO‐induced increase in polyamine uptake." (PMID 39981745, 2025). "In contrast, SLC3A2 overexpression did not enhance polyamine uptake in neuroblastoma cells." (PMID 39981745, 2025).
clear cell renal carcinoma (6 papers, 2013 to 2024). A malignant epithelial neoplasm of the kidney characterized by the presence of lipid-containing clear cells within a vascular network. "SLC3A2 knockdown in clear cell renal cancer cells suppressed cell spreading, migration, and attenuated the adhesion-induced sustained FAK phosphorylation and activation of the downstream signaling pathways PI3k/Akt and MEK/ERK." (PMID 29179459, 2017).
glioblastoma (6 papers, 2021 to 2025). The most malignant astrocytic tumor (WHO grade IV). "Subsequently, the impact of SLC3A2 on glioblastoma was examined using a U87 orthotopic xenograft mouse model." (PMID 38977800, 2024).
renal carcinoma (6 papers, 2013 to 2022). A carcinoma arising from the epithelium of the renal parenchyma or the renal pelvis. "4F2hc was shown to play a role in tumorigenesis in renal cancer cell lines and in the skin homeostasis of Slc3a2 conditional knockout mice." (PMID 28786956, 2017).